SNORD115-48 (small nucleolar RNA, C/D box 115-48)
Synonyms: HBII-52-48
Gene: Small nucleolar RNA gene on chromosome 15 (25,269,783 to 25,269,858, forward strand). Ensembl gene ENSG00000201634.
Gene Ontology:
Biological process: RNA processing
Cellular component: nucleolus
Homologues: Orthologues: chimpanzee SNORD115 (100% identical), macaque SNORD115 (91% identical), pig SNORD115 (68% identical), rabbit SNORD115 (68% identical). Paralogues in human: SNORD115-32 (87% identical), SNORD115-16 (86% identical), SNORD115-35 (86% identical), SNORD115 (84% identical), SNORD115-11 (84% identical), SNORD115-13 (84% identical), SNORD115-2 (84% identical), SNORD115-29 (84% identical), SNORD115-36 (84% identical), SNORD115-38 (84% identical), SNORD115-39 (84% identical), SNORD115-43 (84% identical), and 37 more.